KIF27 (kinesin family member 27)
Description:
Plays an essential role in motile ciliogenesis.
Synonyms: DKFZp434D0917
Tractability: Antibody: its Gene Ontology location is reachable by antibodies, with medium confidence. PROTAC: ubiquitination databases record sites on it.
Target class: Other cytosolic protein
Gene: Protein-coding gene on chromosome 9 (83,834,099 to 83,921,494, reverse strand). Ensembl gene ENSG00000165115.
Subcellular location: Cytoplasm, cytoskeleton; Cell projection, cilium
Pathways (Reactome):
Hemostasis: Kinesins
Vesicle-mediated transport: COPI-dependent Golgi-to-ER retrograde traffic
Gene Ontology:
Molecular function: protein binding; ATP binding; microtubule binding; microtubule motor activity
Biological process: cilium assembly; microtubule-based movement
Cellular component: cilium; kinesin complex; cytoskeleton
Genetic constraint (gnomAD): Loss-of-function variants: 71 observed, 110.9 expected, observed/expected ratio (o/e) 0.64, 90% interval 0.53 to 0.78. The upper end of that interval is the gene's LOEUF score, 0.78, which puts it in group 3 of 6, group 1 being the genes least tolerant of losing a copy. Missense variants: 1,110 observed, 1,394.5 expected, observed/expected ratio (o/e) 0.8, 90% interval 0.76 to 0.84. Synonymous variants: 411 observed, 492.67 expected, observed/expected ratio (o/e) 0.83, 90% interval 0.77 to 0.9.
Homologues: Orthologues: macaque KIF27 (96% identical), pig KIF27 (88% identical), dog KIF27 (86% identical), rabbit KIF27 (85% identical), mouse Kif27 (79% identical), rat Kif27 (78% identical), guinea pig KIF27 (77% identical), tropical clawed frog kif27 (59% identical). Paralogues in human: KIF7 (39% identical), KIF21A (24% identical), KIF4A (23% identical), KIF21B (22% identical), KIF4B (22% identical), CENPE (22% identical), KIF15 (18% identical), KIF5C (17% identical), KIF5A (17% identical), KIF5B (17% identical), KIF13B (17% identical), KIF16B (17% identical), and 29 more.
Diseases named in the same sentence as KIF27 in open-access papers:
KIF27 is named in the same sentence as 4 diseases in open-access papers, as found by Europe PMC text mining. Sharing a sentence is not in itself a finding about the gene and the disease.
KIF27 shares sentences with these, for which no sentence is quoted: tumor (3 papers); cancer (2); Anxiety (1); Bardet-Biedl syndrome (1).